RTN4R (reticulon 4 receptor)
Description:
Receptor for RTN4, OMG and MAG. Functions as a receptor for the sialylated gangliosides GT1b and GM1. Besides, functions as a receptor for chondroitin sulfate proteoglycans (By similarity). Can also bind heparin (By similarity). Intracellular signaling cascades are triggered via the coreceptor NGFR. Signaling mediates activation of Rho and downstream reorganization of the actin cytoskeleton. Mediates axonal growth inhibition. Plays a role in regulating axon regeneration and neuronal plasticity in the adult central nervous system. Plays a role in postnatal brain development. Required for normal axon migration across the brain midline and normal formation of the corpus callosum. Protects motoneurons against apoptosis; protection against apoptosis is probably mediated via interaction with MAG. Acts in conjunction with RTN4 and LINGO1 in regulating neuronal precursor cell motility during cortical development. Like other family members, plays a role in restricting the number dendritic spines and the number of synapses that are formed during brain development. (Microbial infection) Acts as a receptor for Reovirus type 3.
Synonyms: NgR; NOGOR; NgR1
Tractability: Small molecule: it belongs to a druggable protein family. Antibody: UniProt places it where antibodies can reach, with high confidence; its Gene Ontology location is reachable by antibodies, with high confidence; UniProt predicts a signal peptide or a membrane-spanning region. PROTAC: its protein half-life has been measured.
Gene: Protein-coding gene on chromosome 22 (20,241,415 to 20,283,246, reverse strand). Ensembl gene ENSG00000040608.
Subcellular location: Cell membrane; Membrane raft; Cell projection, dendrite; Cell projection, axon; Perikaryon
Subcellular location (Human Protein Atlas): Focal adhesion sites; Plasma membrane; Actin filaments
Pathways (Reactome):
Signal Transduction: Axonal growth inhibition (RHOA activation)
Gene Ontology:
Molecular function: ganglioside GM1 binding; ganglioside GT1b binding; protein binding; chondroitin sulfate binding; heparin binding; neuregulin receptor activity; signaling receptor activity
Biological process: positive regulation of Rho protein signal transduction; cell surface receptor signaling pathway; corpus callosum development; negative regulation of axon extension; negative regulation of axon regeneration; negative regulation of neuron projection development; neuronal signal transduction; positive regulation of GTPase activity; regulation of postsynapse assembly; regulation of synapse assembly
Cellular component: cell surface; endoplasmic reticulum; external side of plasma membrane; extracellular exosome; membrane raft; plasma membrane; axonal growth cone; dendritic shaft; neuron projection; neuronal cell body; perikaryon; axon; dendrite; glutamatergic synapse; growth cone
Genetic constraint (gnomAD): Loss-of-function variants: 3 observed, 24.94 expected, observed/expected ratio (o/e) 0.12, 90% interval 0.054 to 0.31. The upper end of that interval is the gene's LOEUF score, 0.31, which puts it in group 1 of 6, group 1 being the genes least tolerant of losing a copy. Missense variants: 542 observed, 671.19 expected, observed/expected ratio (o/e) 0.81, 90% interval 0.75 to 0.87. Synonymous variants: 287 observed, 302 expected, observed/expected ratio (o/e) 0.95, 90% interval 0.86 to 1.05.
Homologues: Orthologues: chimpanzee RTN4R (99% identical), macaque RTN4R (97% identical), mouse Rtn4r (89% identical), pig RTN4R (89% identical), rat Rtn4r (89% identical), dog RTN4R (87% identical), guinea pig RTN4R (81% identical), tropical clawed frog rtn4r (45% identical), zebrafish rtn4r (45% identical). Paralogues in human: RTN4RL1 (38% identical), RTN4RL2 (36% identical), NYX (24% identical), LRRC4 (23% identical), LRRC4B (23% identical), FLRT2 (22% identical), FLRT3 (22% identical), LRRC4C (22% identical), FLRT1 (22% identical), LRRTM3 (21% identical), LRRTM4 (21% identical), LRRC15 (21% identical), and 10 more.
Diseases named in the same sentence as RTN4R in open-access papers:
RTN4R is named in the same sentence as 108 diseases in open-access papers, as found by Europe PMC text mining. Sharing a sentence is not in itself a finding about the gene and the disease. The quoted sentences say what the papers report.
schizophrenia (13 papers, 2006 to 2023). A major psychotic disorder characterized by abnormalities in the perception or expression of reality. "Mouse models have been developed based on schizophrenia-associated genetic variants involved in small GTPase RhoA signaling, including variants affecting the Arhgap10, Kalrn, and Rtn4r genes, and their phenotypic characterization has been performed." (PMID 37958606, 2023). "Participant 120 is a 36-month-old male who showed a very small gain at 22q11.21 which contains the RTN4R gene for susceptibility to schizophrenia by encoding a protein component of myelin and preventing axonal regeneration." (PMID 25400949, 2014). "It is therefore conceivable that RTN4R deficiency facilitates the effect of other schizophrenia susceptibility genes or disease-related pathological processes by destabilizing relevant neural circuits during development." (PMID 18043741, 2007). "We found weak sex-specific evidence for association between common RTN4R polymorphisms and schizophrenia in the Afrikaner patients." (PMID 18043741, 2007). "In this context, the location of RTN4R within the replicated and highly penetrant 22q11.2 schizophrenia susceptibility locus makes the gene a prime candidate for influencing disease susceptibility." (PMID 18043741, 2007). "Here, we undertake a comprehensive multi-pronged approach to explore the possibility that RTN4R is a schizophrenia susceptibility gene from the 22q11.2 locus." (PMID 18043741, 2007). "In our study, the sample of several hundred chromosomes does not have sufficient power for our results to be considered unequivocal in proving the association between rare variants of RTN4R and schizophrenia." (PMID 18043741, 2007). "Because schizophrenia is associated with deletion of 22q11.2, where RTN4R is located, these reports suggest that RTN4R expression may contribute to the etiology of schizophrenia." (PMID 37958606, 2023). "RTN4R (reticulon 4 receptor), which is an essential role in axonal regeneration and structural plasticity in the central nervous system, has been elucidated to be associated with the risk for sporadic amyotrophic lateral sclerosis and schizophrenia." (PMID 32266149, 2020). "The protein NgR1 is encoded by RTN4R, a gene linked to schizophrenia." (PMID 27468420, 2016). "The presence of novel nonsynonymous variants in RTN4R was previously reported in schizophrenia." (PMID 27468420, 2016). "However, two preliminary reports described sex-specific associations between schizophrenia and common variants in the RTN4R gene, as well as its ligand RTN4." (PMID 18043741, 2007). "Since it has been suggested that variants in RTN4R may affect schizophrenia susceptibility differently in males and females we conducted both combined and sex-stratified analyses." (PMID 18043741, 2007). "Given the difficulties in assessing the significance of association to rare variants, primarily due to a lack of power, we sought to obtain additional supportive data by testing for independent association with common variants of RTN4R in families with schizophrenia." (PMID 18043741, 2007). "In order to complement our human genetic studies (see Discussion), we generated a mouse model that is deficient in the Rtn4r gene and probed for deficits in phenotypic components, which include endophenotypes associated with schizophrenia that can be modeled reliably in mice." (PMID 18043741, 2007). "However, they suggest that RTN4R may modulate the genetic risk or clinical expression of schizophrenia in a subset of patients and identify additional studies that will be necessary to clarify the role of RTN4R in psychiatric phenotypes." (PMID 18043741, 2007). "In a post-mortem brain analysis, the expression levels of RTN4R were decreased in the dorsolateral prefrontal cortex but increased in the hippocampal CA3 region of patients with schizophrenia compared to healthy controls." (PMID 37958606, 2023).
schizophrenia (continued). "In this study, we analyzed two unrelated schizophrenia populations for mutations in LGI1 and RTN4R (NgR1)." (PMID 27468420, 2016). "In our complementary mouse model studies, we identified a haploinsufficient effect of Rtn4r on locomotor activity, but normal performance in schizophrenia-related behavioral tasks." (PMID 18043741, 2007). "We sequenced exon II of RTN4R in 208 individuals with schizophrenia from the U.S. (European ancestry) and identified five variants." (PMID 18043741, 2007). "The Nogo-66 receptor gene (RTN4R) is a GPI anchored protein implicated in axonal growth inhibition, and a candidate for a schizophrenia susceptibility gene." (PMID 16846510, 2006). "RTN4R (also called Nogo-66 receptor, NgR1) is a RTN4 receptor subunit located at chr22q11.2, and it has been shown that deletion of chr22q11.2 is associated with a high risk of developing schizophrenia." (PMID 37958606, 2023). "In addition, variants in genes that activate RhoA via GEF, such as RTN4R, or in those that degrade RhoA, such as KCTD13, were also identified in schizophrenia." (PMID 37958606, 2023). "RTN4R is upregulated in the brains of patients with schizophrenia." (PMID 24478629, 2014). "In addition, this participant also had a very small 22q11.21 duplication including the PRODH and RTN4R genes both reportedly play a role in schizophrenia." (PMID 25400949, 2014). "Genetic evidence supports a role of RTN4R in the etiopathogenesis of schizophrenia." (PMID 24478629, 2014). "Moreover, alterations in the levels of RTN4R or two RTN4R ligands have been described in postmortem analyses of brains from individuals with schizophrenia." (PMID 18043741, 2007). "Our results do not support a major role of RTN4R in susceptibility to schizophrenia or the cognitive and behavioral deficits observed in individuals with 22q11 microdeletions." (PMID 18043741, 2007). "Stratification by sex provided weak evidence for an association between RTN4R and schizophrenia, which did not survive a conservative Bonferroni correction." (PMID 18043741, 2007). "In the U.S. sample, we identified two novel non-conservative RTN4R coding variants in two patients with schizophrenia that were absent in 600 control chromosomes." (PMID 18043741, 2007). "Our results do not support a major role of RTN4R in susceptibility to schizophrenia or in the cognitive and behavioral deficits observed in individuals with 22q11 microdeletions." (PMID 18043741, 2007). "However, the identification of the previously reported R399W mutation in RTN4R and the existence of three distinct LGI1 mutations raise the possibility that these genes may be involved in schizophrenia pathogenesis." (PMID 27468420, 2016). "Interestingly, in vitro experiments demonstrated that cultured neurons expressing the schizophrenia-associated RTN4R variants failed to respond to the growth inhibiting activity of myelin, and functioned as a dominant negative to disrupt endogenous RTN4R." (PMID 24478629, 2014). "The screening of RTN4R and LGI1 genes did not indicate that these genes are common variants associated with schizophrenia." (PMID 27468420, 2016). "We also identified rare non-synonymous changes within the RTN4R gene of schizophrenia patients but not in unaffected controls." (PMID 18043741, 2007).
multiple sclerosis (8 papers, 2013 to 2023). A progressive autoimmune disorder affecting the central nervous system resulting in demyelination. "Although no approved drugs, an antagonist for RTN4R was in clinical trials for the treatment of multiple sclerosis (however no development has been reported in such trials)." (PMID 38030643, 2023).
Insulin resistance (5 papers, 2018 to 2025). Increased resistance towards insulin, that is, diminished effectiveness of insulin in reducing blood glucose levels. "These unadjusted associations identified species that have been associated with insulin resistance and obesity for the protein (eg, CES1, INHBC, RTN4R), metabolite (α-aminoadipate, butyryl carnitine, tyrosine), and lipid (TG and DG species) assays." (PMID 39657693, 2025).
sporadic amyotrophic lateral sclerosis (2 papers, 2018 to 2020). Sporadic amyotrophic lateral sclerosis is a amyotrophic lateral sclerosis in which there is no known cause, such as no family history. "Single-nucleotide polymorphisms (SNPs) in the Nogo-A receptor gene (RTN4R) have been associated with increased risk for sporadic amyotrophic lateral sclerosis (SALS) in the French population." (PMID 29706887, 2018).
delirium (1 paper, 2018). A disorder characterized by confusion; inattentiveness; disorientation; illusions; hallucinations; agitation; and in some instances autonomic nervous system overactivity. "Five proteins (CHI3L1, IL6, SFRP2, PMP2, and RTN4R) differed in serum in patients with postoperative delirium compared to baseline with corrected p < 0.01 and 11 at p < 0.05." (PMID 30367354, 2018).
migraine (1 paper, 2019). "Here we investigated a potential link between migraine and five key Nogo-type signaling genes: RTN4, OMGP, MAG, RTN4R and LINGO1, by screening 15 single nucleotide polymorphisms (SNPs) within these genes." (PMID 31861860, 2019).
steatosis (1 paper, 2023). Increased lipid within the cytoplasm of cells. "RTN4R has important roles in regulating axon regeneration and neuronal plasticity in the central nervous system, but the canonical ligand for RTN4R (reticulin 4) is also expressed in non-parenchymal cells within the liver where it blocks diet-induced hepatic lipid accumulation, steatosis and IR." (PMID 37329449, 2023).
cancer (10 papers, 2019 to 2025). A tumor composed of atypical neoplastic, often pleomorphic cells that invade other tissues. "We also found the genotype of rs16879870 and rs854936 was significantly associated with the expression of gene GJB7 (P = 0.013) and RTN4R (P = 0.047) in cancer tissues of TCGA, respectively." (PMID 32266149, 2020). "That findings indicated that RTN4R might be a new risk factor for predicting cancer prognosis." (PMID 32266149, 2020). "The gene expression of GJB7 and RTN4R in cancer tissues were obviously higher than normal tissues (P = 5.42 × 10−8 and 4.55 × 10−12 for GJB7 and RTN4R, respectively)." (PMID 32266149, 2020). "In upregulated genes of both NB primary tumor escape and metastasis of NC-derived cancers signatures, we noticed RTN4R/NogoR, one of the first characterized direct receptor of OLFM123." (PMID 35538114, 2022). "Although the roles of other genes involved in the prognostic model have been relatively less explored, some bioinformatics analyses have identified the prognostic role of some of these genes, such as RTN4R, FCGBP, and FST, in OSCC or other types of cancers." (PMID 36185403, 2022).
brain diseases (1 paper, 2021). "Almost half of them were involved in axon-related processes (RTN4R, CNTNAP4, ADAM22, PCSK1N, NRXN1), which could indicate that the neurodegenerative mechanisms may be different between these brain diseases." (PMID 33603109, 2021).
RTN4R also shares sentences with these, for which no sentence is quoted: Stroke (15 papers); Alzheimer disease (9); ischemic stroke (9); Cerebral ischemia (8); spinal cord injury (8); diabetes (6); experimental autoimmune encephalomyelitis (6); myocardial infarction (6); tumor (6); amyloid (5); Cognitive impairment (5); neurodegenerative disease (5); amyotrophic lateral sclerosis (4); brain injury (4); demyelination (4); diabetic cardiomyopathy (4); diabetic nephropathy (4); glioma (4); Hyperglycemia (4); Myocardial fibrosis (4); neurological diseases (4); Anxiety (3); breast carcinoma (3); cardiac hypertrophy (3); cardiovascular disease (3); cerebral infarction (3); colorectal cancer (3); epilepsy (3); glaucoma (3); glioblastoma (3).
A further 69 diseases each share a sentence with RTN4R in 3 papers or fewer.